DNASE1L1 (deoxyribonuclease 1 like 1)
Synonyms: DNAS1L1; DNL1L; XIB; DNASEX; G4.8
Tractability: Antibody: its Gene Ontology location is reachable by antibodies, with high confidence; UniProt predicts a signal peptide or a membrane-spanning region.
Gene: Protein-coding gene on chromosome X (154,401,236 to 154,412,114, reverse strand). Ensembl gene ENSG00000013563.
Subcellular location: Endoplasmic reticulum
Pathways (Reactome):
Immune System: Neutrophil degranulation
Gene Ontology:
Molecular function: protein binding; deoxyribonuclease I activity; DNA binding; DNA nuclease activity; catalytic activity
Biological process: DNA catabolic process; DNA metabolic process
Cellular component: endoplasmic reticulum; extracellular region; nucleus; specific granule lumen
Homologues: Orthologues: chimpanzee DNASE1L1 (99% identical), macaque DNASE1L1 (97% identical), pig DNASE1L1 (80% identical), dog DNASE1L1 (80% identical), rabbit DNASE1L1 (79% identical), guinea pig DNASE1L1 (71% identical), mouse Dnase1l1 (70% identical), rat Dnase1l1 (67% identical), zebrafish dnase1l1 (41% identical), tropical clawed frog DNASE1L1 (41% identical). Paralogues in human: DNASE1L3 (39% identical), DNASE1L2 (37% identical), DNASE1 (34% identical).
Diseases named in the same sentence as DNASE1L1 in open-access papers:
DNASE1L1 is named in the same sentence as 10 diseases in open-access papers, as found by Europe PMC text mining. Sharing a sentence is not in itself a finding about the gene and the disease. The quoted sentences say what the papers report.
co-infection (1 paper, 2025). "Regarding the co-infection of cells by E. coli and S. aureus, the unique genes of ES2 are DZIP1 and SMTNL2; the unique genes of ES3 are ALDH4A1, DNASE1L1, FAM227A, and KAT2B; and ES1 has 143 unique genes." (PMID 40771952, 2025).
cystic teratoma (1 paper, 2024). "In summary, amplifications of EVX2, HOXD13, HOXD12, HOXD11, HOXD10, and HOXD9 on 2q31.1, NDUFV1 on 11q13.2, and RPL10, SNORA70, DNASE1L1, TAZ, ATP6AP1, and GDI1 on Xq28 were found in all nine mature cystic teratomas in this study." (PMID 38907278, 2024). "Amplifications and deletions of large DNA fragments were observed in some samples, while amplifications of EVX2 and HOXD9-HOXD13 on 2q31.1, NDUFV1 on 11q13.2, and RPL10, SNORA70, DNASE1L1, TAZ, ATP6AP1, and GDI1 on Xq28 were found in all nine mature cystic teratomas." (PMID 38907278, 2024).
glycogen storage disease (1 paper, 2021). "Another gene of this family, the DNASE1L1, was related to Pompe’s disease in humans, which is a glycogen storage disease characterized by muscle weakness." (PMID 34381378, 2021).
DNASE1L1 also shares sentences with these, for which no sentence is quoted: tumor (6 papers); infection (4); cancer (2); cervical carcinoma (1); COVID-19 (1); neuroblastoma (1); teratoma (1).